IL33 (interleukin 33)
Diseases named in the same sentence as IL33 in open-access papers (continued):
Sharing a sentence is not in itself a finding about the gene and the disease.
ischemic stroke (continued). "Electroacupuncture combined with induced pluripotent stem cell-derived small extracellular vesicles induces neuroprotection in ischemic stroke through downregulation of the IL-33/ST2 axis and reduction of microglial activation." (PMID 36439205, 2022). "Another mechanism involved in IL-33-mediated protection in ischemic stroke is promotion of the T helper type 2 (Th2) response and suppression of Th1 and Th17 responses." (PMID 34079543, 2021). "Conversely, exogenous IL-33 treatment protects mice against experimental ischemic stroke and neonatal hypoxic ischemic brain injury." (PMID 34079543, 2021). "This study is the first in our opinion to match IL‐33 levels to long‐term outcomes and recurrence of ischemic stroke in patients after AIS." (PMID 31397082, 2019). "IL‐33 can be used to predict the long‐term outcomes and ischemic stroke recurrence in first‐ever acute ischemic stroke patients." (PMID 31397082, 2019). "Based on the ROC curve, IL‐33 showed a significantly great ability to predict ischemic stroke recurrence with an AUC of 0.626 (95% CI, 0.537–0.714, p = .016)." (PMID 31397082, 2019). "Recently study show Interleukin-33 (IL-33) and levels of fibrinogen after anticoagulation were related to ischemic stroke." (PMID 30574421, 2018). "IL-33 plasma levels were obviously increased in the ischemic stroke patients (84±4.23 pg/ml) when compared to the healthy volunteers (36.25±11.8 pg/ml)." (PMID 27040385, 2016). "Second, no testing was performed to assay the functional consequences of genetic variation in individual patients, such as plasma or tissue levels of IL-33, and the association between SNPs in IL33 and ischemic stroke is conjectural." (PMID 24107076, 2013). "Although several reports suggest that polymorphisms in IL-33 gene play important roles in the development of cardio-cerebral vascular disease, the association of polymorphisms of IL33 with human ischemic stroke is still unclear." (PMID 24107076, 2013). "This study analyzed SNPs in the IL33 gene in Chinese patients with ischemic stroke for the first time." (PMID 24107076, 2013). "Aptamers against sST2 may be an available approach for detecting sST2 concentrations and restoring the protective effects of IL-33/ST2 against ischemic stroke." (PMID 40376266, 2025). "Fourth, although one study identified a significant association between the IL-33 gene polymorphism rs4742170 and ischemic stroke development, this study did not examine genetic variations." (PMID 39650246, 2024). "Additionally, we showed that exogenous IL-33 was effective to improve blood–brain barrier leakage and functional recovery after ischemic stroke." (PMID 37968698, 2023). "In rat models of ischemic stroke, the expression of IL-33 and ST2 was elevated, which suppressed neuronal damage by promoting microglial polarization toward the M2 phenotype and cytokine production associated with the M2 macrophage-like microglial immune phenotype." (PMID 35974336, 2022). "Nevertheless, the functions of IL-33 in ischemic stroke remain disputable." (PMID 35269441, 2022). "Accumulating literature demonstrates an anti-inflammatory role for IL-33 in ischemic stroke." (PMID 36439205, 2022). "IL-33 also protects ischemic stroke injury by regulating specific microglial activities." (PMID 35173738, 2022). "In ischemic stroke patients, IL-33 plasma level was found to be significantly elevated." (PMID 35269441, 2022). "The concentrations of both IL-33 and sST2 increase in circulating blood in patients with ischemic stroke, and both are negatively correlated with patient outcome and can serve as independent diagnostic and predictive prognostic markers in ischemic stroke patients." (PMID 34079543, 2021). "In recent years, IL-33 has been found to be involved in various disorders of the central nervous system (CNS), including multiple sclerosis (MS), infection, ischemic stroke, traumatic brain injury (TBI), spinal cord injury (SCI), brain tumorigenesis, and mental disorders." (PMID 34079543, 2021).
ischemic stroke (continued). "Interleukin-33 might have therapeutic effects on ischemic stroke by promoting macrophage M2 polarization and cytokine production." (PMID 34650552, 2021). "The involvement of IL-33 in the course of ischemic stroke has been widely reported." (PMID 33854693, 2021). "Interestingly, recent studies have reported the immunoregulatory effects of IL-33 in a mouse model of ischemic stroke." (PMID 32859229, 2020). "However, the effects of IL‐33 levels on long‐term functional outcome and recurrent ischemic stroke in AIS patients are still uncertain." (PMID 31397082, 2019). "One recent research demonstrated that the genetic variation in IL‐33 was significantly related to risk of ischemic stroke in north Chinese population (Guo, Zhou, Guo, Zhang, & Sun, 2013)." (PMID 31397082, 2019). "In addition, the elevated levels of IL-17, IL-33 and IL-6 were found in the plasma of patients with ischemic stroke, as well as in the supernatants of the cell monocyte stimulated by HMGB1." (PMID 27040385, 2016). "A recent study found that IL-33 could play a protective role after ischemic stroke in animals; IL-33 treatment via the intracerebroventricular route decreased infarction size." (PMID 27699084, 2016). "In conclusion, our findings supported genetic variation of rs4742170 in IL33 gene as a modest protective factor for ischemic stroke in North Chinese, and provided further contribution toward new opportunities to investigate ischemic stroke pathogenesis, treatment, and prevention." (PMID 24107076, 2013). "Additional studies support the significance of low IL-33 levels in predicting long-term outcomes in patients with first-ever acute ischemic stroke, with one such study noting a closely related adjusted hazard ratio of 0.979 (95% CI, 0.961–0.997, P = 0.025) for recurrent ischemic stroke." (PMID 39650246, 2024). "In addition to ischemic stroke, the relationship between IL-33 and ICH has gradually been reported." (PMID 33854693, 2021). "In summary, IL-33 treatment might be a promising therapeutic method for ischemic stroke patients." (PMID 34079543, 2021). "Therefore, the measurement of IL‐33 level might be considered as a predictive factor for the long‐term outcomes and ischemic stroke recurrence." (PMID 31397082, 2019). "The IL-33/ST2 pathway plays a critical role in neuroinflammation-related CNS diseases, including ischemic stroke." (PMID 40376266, 2025). "In the mouse model of ischemic stroke induced by middle cerebral artery occlusion (MCAO), IL-33 mRNA and protein expression are obviously upregulated in lesions, and mature oligodendrocytes and astrocytes are responsible for this upregulation." (PMID 34079543, 2021). "However, it is not clear how genetic variants in IL33 might affect its function to reduce the risk of ischemic stroke." (PMID 24107076, 2013). "After ischemic stroke, administration of glyceryl triacetate (GTA) resulted in enhanced lipogenesis and exogenous IL-33 upregulation, could lead to improved repair of the BBB damage." (PMID 38980021, 2024). "Additionally, patients with large artery ischemic strokes exhibited significantly higher median IL-33 levels (47.4 pg/ml [IQR, 30.5–55.1]) compared to those with other ischemic stroke subtypes (54.2 pg/ml [IQR, 37.2–71.3]; P = 0.013)." (PMID 39650246, 2024). "Finally, the possible mechanisms driving the dual effects of IL-33 on cognitive function in neurological disorders are discussed, particularly in AD, MS, TBI, ischemic stroke, and CNS infections." (PMID 35974336, 2022). "Serum IL‐33 level was significantly lower in patients with recurrent ischemic stroke as compared to those without recurrence (50.68 ± 17.26 ng/ml vs. 60.06 ± 20.91 ng/ml, p = .011]." (PMID 31397082, 2019). "Therefore, we hypothesized that GTA would promote lipogenesis the peri-infarct after ischemic stroke and contribute to the BBB repair through IL-33." (PMID 37968698, 2023).
ischemic stroke (continued). "Increasing evidence has demonstrated that IL-33/ST2 signaling plays diverse but crucial roles in the homeostasis of the central nervous system (CNS) and the pathogenesis of CNS diseases, including neurodegenerative diseases, cerebrovascular diseases, infection, trauma, and ischemic stroke." (PMID 34079543, 2021). "Additionally, IL33 rs7025417 and IL33 rs4742170, which is in high linkage disequilibrium with IL33 rs7025417, have been related to coronary artery disease (CAD) and ischemic stroke in non-rheumatic Chinese individuals, respectively." (PMID 26571131, 2015).
systemic sclerosis (25 papers, 2013 to 2024). A chronic disorder, possibly autoimmune, marked by excessive production of collagen which results in hardening and thickening of body tissues. "IL-33 has been implicated in the skin fibrosis seen in systemic sclerosis (SSc), an autoimmune fibrotic disease of the skin, internal organs, and blood vessels, which has the highest mortality of the rheumatic diseases." (PMID 38566909, 2022). "Similarly, IL-33 shows promise, particularly in systemic sclerosis, due to its association with right ventricular dysfunction; however, its applicability is limited by a lack of standardization." (PMID 39859001, 2024). "The role of RAGE in skin remodeling and systemic sclerosis is already a defined process, worth mentioning also in this review: among other alarmins such as IL-33 and IL-1α, HMGB1 seems to play a major role as a ligand for the RAGE receptor." (PMID 33435332, 2021). "Recent articles have described IL-33 as an emerging pro-fibrotic cytokine in the immune system as well as a novel potential target for systemic sclerosis." (PMID 30498500, 2018). "Here, we review the available information and focus on the pleiotropic expression and pathogenesis of IL-33 in systemic sclerosis, as well as the feasibility of using IL-33 in clinical applications." (PMID 30498500, 2018). "Serum levels of IL-33 are elevated in patients with systemic sclerosis, a connective tissue disease characterized by fibrosis of the skin and other organs, such as the lungs." (PMID 26549942, 2015). "Dermal and pulmonary fibroblasts showed nuclear IL-33 expression in patients with systemic sclerosis." (PMID 23567618, 2013). "Our results show that two interleukins, IL-13 and IL-33, closely related to one another, are increased in a specific subset of systemic sclerosis patients with interstitial lung disease, a relevant complication conferring a high risk for mortality and morbidity." (PMID 35252259, 2022). "In a mouse model of systemic sclerosis, the IL-4-producing cell proportion was significantly higher in wild-type Tregs co-cultured with Fli1+/- fibroblasts (which overproduced IL-33) than in those co-cultured with wild-type fibroblasts, which were canceled by neutralizing anti-IL-33 antibody." (PMID 36428461, 2022). "However, in allergic airway disease and systemic sclerosis, IL-33/ST2 can dysregulate lung and skin Treg cells and impair its suppressive ability, respectively." (PMID 32908451, 2020). "The authors also demonstrated that primary pulmonary fibroblasts derived from the lungs of the patients with IPF and systemic sclerosis, showed enhanced expression of IL-33 mRNA, suggesting that the fibroblasts may be an important source of IL-33." (PMID 28202030, 2017). "Importantly, IL-33 mRNA and protein levels have been found significantly increased in the bronchoalveolar lavage (BAL) fluids of patients with IPF and systemic sclerosis (SSc)-related fibrosis as compared to healthy controls." (PMID 30405626, 2018).
multiple sclerosis (24 papers, 2016 to 2025). A progressive autoimmune disorder affecting the central nervous system resulting in demyelination. "Bacterial species that were more abundant in cases with disease-active treatment-naïve multiple sclerosis were positively linked to a group of plasma cytokines including IL-22, IL-17A, IFN-β, IL-33, and TNF-α." (PMID 36604748, 2023). "A study in the United States found that the levels of IL-33 in the periphery and the center of patients with multiple sclerosis (MS) increased, suggesting that IL-33 is an important factor involved in MS." (PMID 33854693, 2021). "In experimental autoimmune encephalitis (EAE), a mouse model for multiple sclerosis (MS), IL-33 plays a protective role by dampening the generation of inflammatory astrocytes and the expansion of effector T cells, while enhancing TREG and TH2 responses." (PMID 30949175, 2019). "Higher CSF Fetuin-A and IL-33 levels are strongly correlated with multiple sclerosis." (PMID 39050669, 2024). "IL-33 is mainly localized in astrocytes after spinal cord injury, while being widely expressed in microglia, neurons, oligodendrocytes and astrocytes in multiple sclerosis." (PMID 35432343, 2022). "In patients with multiple sclerosis (MS), the expression of ST2 and IL-33 is upregulated in brain lesions compared to healthy individuals." (PMID 37892176, 2023). "Furthermore, IL-33 may play a role of inhibitor of myelination in multiple sclerosis model." (PMID 28448579, 2017). "The relevance of IL-33/ST2 signaling as a regulator of Treg populations has been documented in both steady-state conditions and various diseases, including gastrointestinal disease, lung disease, cancer, multiple sclerosis, and other autoimmune models." (PMID 38566998, 2024). "In addition, through GABA-mediated pathways homotaurine has anti-inflammatory and therapeutic properties in a multiple sclerosis animal model, even involving increased IL-10-secreting responses, but unfortunately IL-18 and IL-33 cytokines have not been evaluated in that context." (PMID 35515001, 2022).
lung diseases (23 papers, 2015 to 2026). "This article provides an overview of the mechanisms and related targets of IL-33 in the development of lung diseases caused by Type 2 inflammation, and summarizes the associated treatment methods." (PMID 39301028, 2024). "studying a cystic fibrosis-like lung disease model, compared IL-33 gene knockout (IL-33KO) Tg+ mice with IL-33 heterozygous (IL-33HET) Tg+ mice." (PMID 39301028, 2024). "Ultimately, it is important to clarify the intricate function of IL-33 in lung diseases, driving the elaboration of innovative approaches for immune treatment." (PMID 36675299, 2023). "Similar to cases of exposure to known respiratory virus infections, exposure to SARS-CoV-2 induces the expression of IL-33, correlating with T-cell activation and lung disease severity." (PMID 36498859, 2022). "Further studies are needed to comprehensively define the contributive role of IL-33 and superantigens to angiogenesis in pulmonary disorders." (PMID 33445787, 2021). "The interleukin-1-type cytokine IL-33 acts as an “alarmin” or damage signal that facilitates the recruitment of inflammatory cells in T helper-2 (Th2) immune cell models of lung disease." (PMID 33376451, 2020). "The interleukin-1 family member IL-33 participates in both innate and adaptive T helper-2 immune cell responses in models of lung disease." (PMID 33376451, 2020). "Therefore, the balance of Treg and Th17 cells can be regulated by adjusting the expression of cytokines such as IL-17A, IL-6, IL-23, IL-33 and Foxp3 to achieve the goal of treating lung diseases." (PMID 37795866, 2023). "Third, considering the redundant nature of cytokines, future studies should focus on whether combined targeting of IL‐25/IL‐33/TSLP is necessary to completely block the progressive fibrotic lung diseases." (PMID 36082495, 2022). "Our results suggest that IL-33 might enhance the inflammatory, angiogenic and lymphangiogenic activities of lung mast cells in pulmonary disorders." (PMID 33445787, 2021). "The IL-33-mediated signal pathway is also required for pulmonary diseases." (PMID 32390869, 2020). "Interestingly, IL-33 expression is markedly decreased in blood vessels of patients with idiopathic pulmonary arterial hypertension, suggesting that IL-33 plays a dynamic role in lung diseases." (PMID 32903501, 2020). "The IL-33/ST2 axis also represents an essential pathway for pulmonary lesion and lung disease progression." (PMID 35888173, 2022). "While deficiency in IL-33 signaling attenuated infection-induced ILC2 numbers and their production of IL-13 and IL-5 in these studies, it remained unclear, whether ILC2s and their cytokine production significantly contributed to AAM differentiation and the severity of pulmonary disease." (PMID 32117319, 2020). "Receiver operating characteristic curves of the TSLP and IL-33 levels revealed clear differences between the IPF and NC groups (AUC = 0.655 and 0.706, respectively), as well as between the IPF and the other lung disease groups (AUC = 0.786 and 0.781, respectively)." (PMID 28202030, 2017). "Given that clinical studies targeting the systemic IL-33 signaling pathway are currently underway in the treatment of COPD (clinicaltrials.gov; NCT04701983; NCT03615040), investigating the role of IL-33 in HLA-DRB1+ RA and lung diseases resulting from airborne exposures may be warranted." (PMID 35717175, 2022).